INS (insulin)
Diseases named in the same sentence as INS in open-access papers (continued):
Sharing a sentence is not in itself a finding about the gene and the disease.
Insulin resistance (continued). "A constant component of the DE pathomechanism is neuroinflammation, which is caused by a complete lack of insulin (e.g., in T1D) or the ineffective action of insulin due to insulin resistance (e.g., in type T2D, which most often co-occurs with obesity)." (PMID 39062768, 2024). "In T2D, insulin resistance occurs when cells, particularly the insulin receptors in the muscle, fat, and liver cells, do not respond adequately to insulin." (PMID 38542928, 2024). "Disruption of insulin signalling by ApoE4 leads to impaired PINK1 activation in cultured neurons and therefore suggests a mechanistic connection between the frequently observed neurodegenerative phenotypes of insulin resistance and mitochondrial dysfunction." (PMID 38504131, 2024). "As a result, HOMA-IR became a commonly used method to assess insulin resistance, as it does not require routine measurement of insulin levels in clinical settings." (PMID 38449844, 2024). "There were no significant changes in body weight, BMI, glucose, insulin or insulin resistance estimated by HOMA-IR in either group during the study period." (PMID 38460092, 2024). "Although measures to study insulin secretion were not performed, this study suggested that even in the context of uncontrolled acromegaly and insulin resistance, insulin still plays a key role in the regulation of circulating IGF-I levels." (PMID 39665021, 2024). "The EK group showed decreased fasting serum insulin (FSI) and homeostatic model assessment for insulin resistance (HOMA-IR) compared to the ob/ob group (FSI: 2.62 ± 0.58 ng/mL vs. 5.66 ± 1.36 ng/mL, p = 0.07; HOMA-IR: 48.30 ± 14.29 vs. 175.13 ± 42.40, p < 0.05)." (PMID 39338296, 2024). "Utilizing a homeostatic model of insulin resistance, Takashina and colleagues discovered a positive correlation between glycine concentration and insulin sensitivity and a negative correlation with insulin resistance." (PMID 39070255, 2024). "First, IR indicators including insulin, HbA1c and the Homeostatic Model Assessment for Insulin Resistance (HOMA-IR) were not measured in the Kailuan study, which limited further comparisons with those conventional biomarkers in the current analysis." (PMID 38898520, 2024). "We analyzed the relationship between SII and indicators of glucose regulation, including fasting plasma glucose, fasting insulin, hemoglobin A1c, oral glucose tolerance test (OGTT), and states of abnormal glucose regulation like impaired glucose tolerance (IGT), insulin resistance, and prediabetes." (PMID 39531415, 2024). "It is noteworthy that, in our study, normal-weight women with E-GDM showed elevated fasting insulin concentrations and HOMA-IR compared with normal-weight and overweight normoglycaemic control participants, suggesting some degree of early-pregnancy insulin resistance." (PMID 39083240, 2024). "Furthermore, hyperandrogenism worsens insulin resistance through various pathways, since it affects the expression of GLUT-4, and inhibits insulin degradation in the liver." (PMID 39459443, 2024). "Regarding insulin resistance, we did not observe significant changes in fasting insulin and HOMA-IR levels." (PMID 39523406, 2024). "Regarding glucose metabolism, a meta-analysis of 12 clinical trials showed that melatonin administration reduced fasting blood glucose, but had no influence on levels of glycated hemoglobin, insulin or insulin resistance (IR)." (PMID 38318471, 2024). "In individuals with insulin resistance, the muscle, fat, and liver cells do not respond normally and require more insulin for glucose entry into cells." (PMID 38254596, 2024). "However, in the context of obesity, interactions between insulin signaling and inflammatory pathways, including STING-IRF3, contribute to insulin resistance." (PMID 39669992, 2024). "Constitutive upregulation of plasma insulin levels without insulin resistance or hypoglycemia suggests that insulin clearance is also impaired in males with CJL." (PMID 39639385, 2024).
Insulin resistance (continued). "Importantly, studies in rodents and humans demonstrated that enhanced BCAA oxidation or dietary restriction of BCAA leads to improved insulin sensitivity 16–20, suggesting that BCAA metabolism plays a role in the pathogenesis of insulin resistance." (PMID 38653240, 2024). "blood-glucose levels are not increased if insulin secretion capacity is sufficient, even in the presence of high insulin resistance." (PMID 40607157, 2024). "Notably, the children in our study were prepubertal (Tanner 1) and had approximately 7 years of age (before the known rise in plasma insulin of adolescence), which may explain the nonsignificant results for the association between plasma adiponectin and insulin resistance." (PMID 38289144, 2024). "A prior study on Gpx KO mice revealed that Gpx1 deficiency enhances insulin signaling in vivo by the inhibition of PTEN, a negative modulator of the PI3K/Akt pathway, to attenuate the development of insulin resistance." (PMID 39383215, 2024). "Chronic inflammation due to obesity or periodontitis, leading to insulin resistance, represents other examples of the negative effect of inflammation on insulin sensibility in dogs." (PMID 38539988, 2024). "Hyperinsulinemia contributes to adipocyte insulin resistance through the activation of the negative feedback loop of the insulin signaling pathway." (PMID 39873003, 2024). "None of the patients developed chronic insulin resistance defined as those requiring more than 200 IU of insulin per day." (PMID 39629677, 2024). "While both AE and REs are recognized as effective interventions for reducing insulin resistance, our research did not identify any advantage of AE in lowering insulin requirements for GDM." (PMID 39481539, 2024). "The insulin concentration was elevated, not at the level of insulin resistance, but it is nonetheless of concern." (PMID 38962449, 2024). "Meta-analyses found that SWS disruption led to increased insulin resistance but did not significantly alter post-prandial glucose or insulin levels in most trials." (PMID 39597994, 2024). "The little available evidence in insulin-injected animals suggests that INSR activation may still be triggered in animal models of AD, even following HFD-induced insulin resistance, similar to the treatment of advanced T2DM." (PMID 37611907, 2024). "Notably, irisin has been shown to enhance PI3K/AKT insulin signaling and reduce the serine phosphorylation of IRS-1 and IRS-2, which are key molecular mechanisms contributing to insulin resistance." (PMID 39769243, 2024). "In the liver RANKL induces insulin resistance by promoting inflammation, whereas in the pancreas RANKL produces a hyperglycaemic state by decreasing insulin production and augments glucagon production which could lead to β-cell dysfunction." (PMID 39588310, 2024). "Insulin resistance (IR) means that the physiological effect of insulin in the body is weakened, the target cells are not sensitive to insulin, and relatively more insulin is required to maintain a normal blood glucose level." (PMID 39139641, 2024). "EA can increase insulin secretion, reduce HOMA-IR, and improve insulin resistance in patients." (PMID 38915316, 2024). "Insulin resistance is known to affect UA metabolism, suggesting that changes in HDL-C levels may indirectly affect SUA levels through changes in insulin sensitivity." (PMID 38977840, 2024). "The gold standard technique for measuring insulin resistance, euglycemic insulin clamp studies, have not been conducted in women with PCOS who are placed on a KD." (PMID 39328462, 2024). "The HOMA-IR index decreased, indicating reduced insulin resistance, although no significant changes in insulin levels were observed in women." (PMID 39458444, 2024).
Insulin resistance (continued). "The homeostasis model assessment of insulin resistance (HOMA-IR), which uses fasting glucose and insulin levels indirectly to assess the degree of IR, is also limited in its widespread clinical use because of the high insulin measurement requirements and poor reproducibility." (PMID 38755682, 2024). "The key pathophysiological feature appears to be a defect in insulin secretory capacity as opposed to peripheral insulin resistance as noted in classical type 2 DM." (PMID 37608126, 2024). "The administration of carrageenan to mice in drinking water can lead to increased glucose intolerance compared to a control group of mice that did not receive this additive, additionally leading to higher insulin levels and greater insulin resistance." (PMID 38892712, 2024). "Βoth studies included patients not receiving insulin treatment at baseline, therefore without profound β-cell dysfunction, highlighting the importance of early interventions targeting obesity-driven insulin resistance." (PMID 38472622, 2024). "Unlike other types of diabetes, it is characterised by insulin resistance developed from placental hormonal release in which the maternal insulin response can no longer compensate for the insulin resistance, resulting in maternal hyperglycaemia." (PMID 38233823, 2024). "Raspberry consumption did not have a significant effect on fasting blood glucose, insulin, hemoglobin A1C, glucose tolerance tests, homeostatic model assessment for insulin resistance, C-reactive protein, and interleukin-6 concentrations." (PMID 38860149, 2024). "This suggests a potential antinatriuretic effect of insulin that is independent of the degree of insulin resistance." (PMID 39167349, 2024). "Insulin resistance (IR) occurs when the main target tissues for insulin action in glucose metabolism do not respond to insulin as they should due to chronic energy surpluses." (PMID 39203828, 2024). "For example, in the case of insulin resistance in the liver, insulin not does suppress hepatic glucose production; however, it does stimulate lipogenesis, causing hyperglycemia, hyperlipidemia and hepatic steatosis." (PMID 38397072, 2024). "In addition, GSEA indicated NF-κB and insulin resistance signaling pathways were inhibited in HFD AAV-USP13 group, while insulin signaling pathways, and fat digestion and absorption signaling pathways were facilitated in HFD AAV-USP13 group." (PMID 39033101, 2024). "Additionally, compared to the CON group, diabetic rats demonstrated reduced glucose tolerance via OGTT, increased insulin levels, and higher HOMA-IR, indicating marked insulin resistance." (PMID 38708085, 2024). "It has been suggested that BAT activation can prevent the development of hyperlipidaemia and obesity by the increased uptake of TGs into BAT independent of insulin and insulin resistance." (PMID 39591977, 2024). "Previous data have shown that LPS binding to TLR4 is associated with insulin resistance, because mice lacking TLR4 are protected from suppressed insulin signaling and insulin-mediated changes in glucose metabolism." (PMID 38257161, 2024). "While criteria to diagnose the presence of insulin resistance have not been well defined, insulin sensitivity is assessed through numerous indices." (PMID 38201980, 2024). "Of note, KITT(iv) is not affected by endogenous insulin unlike HOMA-IR and, thus, the observed associations notably indicated the pathogenetic link of the examined clinical parameters and insulin resistance." (PMID 38905235, 2024). "The causes of insulin resistance in obesity and type 2 diabetes mellitus (T2DM) are not limited to impaired insulin signaling but also involve the complex interplay of multiple metabolic pathways." (PMID 39062577, 2024). "However, obesity is a major contributor to insulin resistance and hyperinsulinemia as it instigates inflammation and consequently increases circulating FFA, adipocytes, and proinflammatory cytokines that impair insulin signaling." (PMID 38540087, 2024).
Insulin resistance (continued). "While we can only compare the insulin sensitivity between the two study arms, comparison with literature shows that the study participants indeed had a low GIR, as expected and consistent with the presence of insulin resistance." (PMID 37922013, 2024). "In the PD group, the increased plasma insulin, impaired fasting glucose, impaired glucose tolerance, HbA1c, and HOMA-IR values in the insulin resistance range may suggest some insulin resistance from peripheral tissue against glucose uptake." (PMID 38612885, 2024). "Looking into the carbohydrates category, glucose and mannose were positively correlated with multiple markers of hyperglycemia and insulin resistance, such as fasting plasma glucose, HbA1C, serum insulin, OGTT AUC glucose, HOMA-IR (Homeostatic Model Assessment for Insulin Resistance), and WHR." (PMID 39195507, 2024). "The present study showed that non-sarcopenic non-obese status is associated with lower fasting insulin levels and HOMA-IR compared to obesity or sarcopenic obesity, indicating a lower state of insulin resistance." (PMID 38612998, 2024). "As a result, this study documents a significant negative correlation between insulin resistance and muscle strength, consistent with previous findings that observed a significant negative correlation between insulin resistance and muscle strength." (PMID 38612885, 2024). "To clarify the contribution of prepubertal weight gain to the development of insulin resistance in PCOS, we investigated the effects of early postnatal overfeeding on inflammatory and energy-sensing pathways as well as on markers of insulin signaling in the liver of the PCOS rat model." (PMID 39268230, 2024). "BF <6 women had increased insulin resistance (higher HOMA-IR and lower Matsuda) and higher insulin secretion (HOMA-B and AUCins/glu) compared with BF ≥6 women (all p≤0.04) at 1 year postpartum; however, these associations were not significant when we adjusted for confounders." (PMID 38772880, 2024). "Other insulin resistance factors, such as dysfunction of insulin signaling and negative impacts on the Akt pathway (i.e., reduction of phosphorylated Akt), on GLUT4 expression, and on insulin receptor/IRS were evidenced." (PMID 38255955, 2024). "HOMA-IR in particular does not include postprandial insulin or glucose in its calculation and thus represents hepatic, but not peripheral, insulin resistance." (PMID 38572086, 2024). "After 8 weeks different diets, the blood glucose and insulin levels of mice in the IR group were higher than those in the control group, while the QUICKI levels were opposite, which confirmed the successful establishment of insulin resistance model mice." (PMID 38528189, 2024). "Therefore, probiotics positively impact insulin resistance and hormonal balance in PCOS by modulating the gut microbiota, increasing SCFAs, reducing systemic inflammation, and improving insulin signaling." (PMID 39599701, 2024). "Only one review analyzed changes in total SCFAs, along with levels of Bifidobacteria and fasting glucose; however, it did not examine the effect of SCFA changes on fasting insulin or homeostatic model assessment of insulin resistance (HOMA-IR)." (PMID 37290429, 2024). "Breastfeeding duration was also related to lower CRP, and lower measures of insulin resistance (HOMA-IR) and insulin secretion (HOMA-B, AUCins/glu), as well as to increased overall insulin sensitivity (Matsuda) and insulin resistance-adjusted insulin secretion (ISSI-2)." (PMID 38772880, 2024). "First, because of the cross-sectional design, it was not possible to track changes in insulin secretion or insulin resistance over time for each individual." (PMID 38188453, 2024). "The random-effects meta-analyses indicated no significant benefit of NMN on fasting glucose, fasting insulin, glycated hemoglobin, homeostatic model assessment for insulin resistance and lipid profile." (PMID 39531138, 2024).
Insulin resistance (continued). "Insulin levels after glucose stimulation in HFHSD-fed male mice increased and sustained the increased level longer than both ND-fed males and females, suggesting elevated insulin resistance in HFHSD-fed males." (PMID 39337631, 2024). "Diminished levels of BVR-A observed in GK rats hippocampus strongly correlate with a well-accepted index of insulin resistance, i.e., HOMA-IR and likely serve as a compensatory mechanism to enhance insulin signaling activation in the setting of reduced insulin sensitivity." (PMID 38843768, 2024). "Insulin resistance is a condition in which target tissues cannot respond to normal levels of insulin, which is often accompanied by the condition of obesity, metabolic syndrome, non-alcoholic fatty liver disease and other metabolic diseases." (PMID 38300233, 2024). "The exact role of zinc in the connection with indexes of insulin resistance and insulin sensitivity is still not fully clarified." (PMID 39596259, 2024). "In SD rats maintained on a fructose-rich diet, which promotes the development of hypertension and insulin resistance, the administration of the ACE inhibitor or AT1R blocker (Olmesartan) significantly reduced blood pressure, improved insulin sensitivity, and reduced adipocyte size." (PMID 38279313, 2024). "Insulin-stimulated spheroids (WA-TNF-α + Insulin) showed significant difference in glucose uptake compared to non-treated spheroids (WA + Insulin), indicating that the TNF-α treatment effectively blocked glucose uptake and induced insulin resistance." (PMID 38820505, 2024). "The obtained values of area under the curve (AUC) indicators indicate the absence of the development of insulin resistance in rats of all experimental groups on the background of consumption of exogenous insulin compared with rats of the Control group." (PMID 38791421, 2024). "Activation of the ERK pathway by insulin was responsible for upregulating EphA2 levels, and this mechanism was independent of insulin resistance." (PMID 39572596, 2024). "Repeated releases of insulin and glucose as a result can contribute to the development of insulin resistance, one of the main negative factors exacerbating fatty liver, as described in Section 2.1." (PMID 39200999, 2024). "Insulin resistance is a condition in which the body's cells do not respond effectively to insulin, a hormone responsible for regulating blood sugar (glucose) levels." (PMID 39713218, 2024). "As a result of insulin resistance, there is an increase in the concentration of insulin, which is not used efficiently by tissues, and secondary hyperinsulinemia, followed by an increase in serum glucose and the development of carbohydrate disorders." (PMID 39457712, 2024). "In contrast, another meta-analysis including RCTs conducted in people with overweight/obesity showed that HbA1c was not reduced following vegetarian diets, nor was fasting insulin, and it did not assess other markers of insulin resistance." (PMID 38999858, 2024). "Normally, insulin suppresses the lipolysis, but in the case of insulin resistance, it fails to restrain lipolysis, but the hepatic lipogenesis is still enhanced, which leads not only to hyperglycemia condition but also induces hepatic steatosis." (PMID 39759127, 2024). "Probiotic and synbiotic supplementation showed significant improvements in insulin resistance (reductions in HOMA-IR, fasting glucose, and insulin), lipid profiles (decreased LDL and triglycerides; increased HDL), and hormonal balance (increased SHBG, decreased total testosterone)." (PMID 39599701, 2024). "By measuring glucose and insulin levels, SIL can improve insulin resistance." (PMID 38645495, 2024). "Further, insulin resistance index (HOMA-IR) was decreased and insulin sensitivity index (HOMA-IS) increased in Lgr4iKO mice fed HFD, suggesting that the increment in glucose tolerance may be attributed to improved peripheral insulin sensitivity." (PMID 38782937, 2024).